ENSG00000201592
Gene: Small nucleolar RNA gene on chromosome X (20,136,306 to 20,136,385, reverse strand). Ensembl gene ENSG00000201592.
Gene Ontology:
Biological process: RNA processing
Cellular component: nucleolus
Homologues: Orthologues: rat LOC120100395 (88% identical), rat LOC120094475 (86% identical), mouse Gm24339 (84% identical).